TNF (tumor necrosis factor)
Diseases named in the same sentence as TNF in open-access papers (continued):
Sharing a sentence is not in itself a finding about the gene and the disease.
memory impairment (continued). "Similarly, our findings indicated that MISO significantly increased the levels of pro‐inflammatory factors (IL‐6, IL‐1β, and TNF‐α) and decreased that of the anti‐inflammatory factor IL‐10 in the hippocampus of offspring mice, which contributed to the observed spatial learning and memory impairment." (PMID 38945806, 2024). "For instance, earlier research in mice and monkeys demonstrated that TNFα (tumor necrosis factor alpha) can induce PKR, which results in memory impairment." (PMID 38068904, 2023). "Lu and colleagues in 2009 reported that silibinin can improve memory impairment, inflammatory responses, and oxidative stress through nitric oxide synthase (NOS) and tumor necrosis factor α (TNFα) inhibition." (PMID 37396937, 2023). "Our results revealed a two-fold increase in IL-1β and TNF-α levels in RSD mice, suggesting synergism in the hippocampus, thus inducing memory impairments." (PMID 36278007, 2022). "Mice in the laparotomy group displayed memory impairment up to POD 14 with initial high levels of inflammatory cytokines in the liver, frontal cortex (IL-1β, IL-6, and TNF-α), and hippocampus (IL-1β and IL-8)." (PMID 29776428, 2018). "However, the exact role of TNFα/PGRN balance in S-DEP-induced memory impairment remains unclear." (PMID 28300056, 2017). "Strawberry and selenium, when administered individually, significantly attenuated memory impairment, oxidative stress, neuroinflammation, and apoptosis, as evidenced by marked normalization of Nrf2/HO-1, TAC, SOD, MDA, TLR4/NF-κB/TNF-α, NLRP3/CASP-1/IL-1β, and BAX/Bcl-2 signaling." (PMID 41471381, 2025). "It significantly modulated the oxidative stress markers (SOD, GSH, CAT, MDA, and NO), inflammatory cytokines (IL-6, IL-1β, TNF-α), neurotrophic factors (CREB, BDNF), apoptotic markers (NFkB, caspase-3, caspase-9), and neurotransmitters (NE, DA, and GABA) in METH-induced memory-impaired rats." (PMID 41010958, 2025). "Tumor-induced memory impairment was found to be accompanied by increased expression of hippocampal TNFα mRNA in the brain (though not upregulation in peripheral plasma TNFα)." (PMID 34200240, 2021). "Nevertheless, our studies provide a new idea that pharmacological blockade of TNF-α and IFN-γ function may offer a potent therapy for microgravity-elicited learning and memory impairment." (PMID 32382569, 2020). "Furthermore, we showed that tumor necrosis factor (TNF) signaling is induced in the CP of AD patients and AD mouse models, whereas TNF receptor 1 (TNFR1) abrogation reduced brain inflammation, blood–CSF barrier impairment and AβO-induced memory impairment." (PMID 34425919, 2021). "However, the reason behind the TNFα up-regulation in S-DEP mice and its mechanism in S-DEP-induced memory impairments remain unknown." (PMID 28300056, 2017).
non-alcoholic steatohepatitis (99 papers, 2011 to 2025). "Previous studies have also reported increases in serum and liver TNF-α levels in patients with nonalcoholic steatohepatitis, with the levels associated with the severity of the histopathology." (PMID 35630624, 2022). "NAC attenuated hepatic oxidative stress and prevented increases in cytochrome P450 2E1 apoprotein, TNF-α expression, and induction of auto-antibodies associated with lipid peroxidation in a dietary polyunsaturated fat model of non-alcoholic steatohepatitis (NASH) in rats." (PMID 26779021, 2015). "Inflammation, mediated by TNF-α and IL-6, promotes non-alcoholic steatohepatitis (NASH) through macrophage infiltration and Kupffer cell activation, leading to hepatic fibrosis and cirrhosis." (PMID 41235339, 2025). "For example, Wilms' tumor 1-associating protein (WTAP) has been reported to be reduced in the liver cell nucleus under phosphorylation by tumor necrosis factor alpha (TNFα) in nonalcoholic steatohepatitis (NASH) condition." (PMID 38368351, 2024). "Xiang reported that kaempferol down-regulated the mRNA expression of TNF-α and IL-6 in a murine model of non-alcoholic steatohepatitis induced by a high-fat diet and exhibited excellent antioxidant and anti-inflammatory activities." (PMID 38630770, 2024). "In general, levels of the systemic inflammatory cytokine TNF-α are known to be elevated in the serum during the progression of both nonalcoholic steatohepatitis and alcoholic liver diseases." (PMID 37759693, 2023). "Regarding TNFα signaling via NF-κB in endothelial cells, in animal studies, Pecam1 KO mouse developed nonalcoholic steatohepatitis, whereas Tlr4 KO mouse and Il15 KO mouse were protected from NAFLD." (PMID 37491046, 2023). "TNF-α has been recently reported to be a potent mediator of ROS production, thus leading to damage of hepatocytes in patients with Non-alcoholic Steatohepatitis, where an increase of EVOLV-6 has also been described." (PMID 37752143, 2023). "The expression levels of pro-inflammatory cytokines, including tumor necrosis factor-α (TNF-α), IL-6, and IL-1β, were significantly decreased in the non-alcoholic steatohepatitis by inhibiting ferroptosis." (PMID 37970439, 2023). "Of interest, we have previously shown that Brg1 can be recruited by NF-κB to the pro-inflammatory mediator promoters including TNF-α and IL-6in the context of non-alcoholic steatohepatitis." (PMID 35614068, 2022). "SLBZS treatment inhibited the TLR4/p38 MAPK signaling pathway, attenuating lipid metabolic disturbance, reducing IL-1β, TNF-α, and IL-6 levels, and reversing non-alcoholic steatohepatitis progression." (PMID 32460745, 2020). "A previous study showed that LPS triggered liver injury by elevating TNF-α in a non-alcoholic steatohepatitis (NASH) model." (PMID 30463239, 2018). "In nonalcoholic steatohepatitis, LPS promote the production of tumor necrosis factor alpha (TNF-α) and other pro-inflammatory cytokines." (PMID 25978374, 2015). "In HFD-fed mice, we found nonalcoholic steatohepatitis, increased gene expression of TNFα, IFNγ, MCP-1, caspase-3, TGFβ1 and collagen α1(I), and increased levels of 3-tyrosine nitrated proteins." (PMID 25261569, 2014). "TNF-α is associated with fat accumulation, particularly NAFLD, and an overexpression of TNF-α mRNA is found in the liver and the adipose tissue of nonalcoholic steatohepatitis patients." (PMID 24864199, 2014). "This is consistent with a previous finding that the IL-10/TNF-α ratio is low in non-alcoholic steatohepatitis (NASH)." (PMID 23285260, 2012). "IL-1β, IL-6, and TNF-α were measured because these cytokines have demonstrated roles as mediators of injury in both alcoholic and nonalcoholic steatohepatitis, and PPAR agonists function in part by regulating proinflammatory responses." (PMID 26339530, 2012).
non-alcoholic steatohepatitis (continued). "With regard to the cytokines, we focused on measuring IL-1β, IL-6, and TNF-α because these have been deemed the most relevant overall to the pathogenesis of alcoholic and non-alcoholic steatohepatitis." (PMID 26339530, 2012). "It was proved that Jiangzhi Granule could reduce nonalcoholic steatohepatitis by inhibiting the M1-type polarization of macrophages mediated by the TNF/NFκB signal." (PMID 38694920, 2024). "This interaction causes the release of TNF-α, which induces the hepatic inflammatory responses and liver fibrosis associated with T2DM, and the progression from non-alcoholic fatty liver disease to nonalcoholic steatohepatitis (NASH)." (PMID 36532552, 2022). "In a study in a non-alcoholic steatohepatitis mouse model, the hot water extract of C. longa inhibited the hepatic production of TNF-α, IL-1β, and IL-6, and in our earlier clinical studies, C. longa extract improved systemic inflammatory markers, including hsCRP, TNF-α, and IL-6." (PMID 36145139, 2022). "Using flow cytometry, we evaluated the plasma levels of IL-1β, IL-6, IL-12, TNF and IL-10 and their association with clinical and biochemical parameters of liver function during simple steatosis (NAFL) and nonalcoholic steatohepatitis (NASH) in biopsy-proven patients." (PMID 34447378, 2021). "In the non-alcoholic steatohepatitis-like model resulting from a HF and high cholesterol (HF-HC) diet, AF reversed the increased liver triglyceride and cholesterol, plasma aspartate aminotransferase, and liver TNFα mRNA levels." (PMID 31680948, 2019). "In the liver these TNF concentrations may only be detectable under specific patho-physiological conditions, such as non-alcoholic steatohepatitis." (PMID 28878689, 2017). "It has long been viewed as a potential antifibrotic agent, in addition to its modulating effect on insulin resistance through downregulation of TNF, it could be a potential mechanism for improvement in patients with nonalcoholic steatohepatitis (NASH)." (PMID 21994862, 2011). "In addition, protein-based biomarkers, such as cytokines like TNF-α and Interleukin 6 (IL-6), have the potential to detect MASLD, suggesting that they can help identify inflammation-related Metabolic Dysfunction-Associated Steatohepatitis (MASH) and more advanced stages of fibrosis." (PMID 40109726, 2025). "Moreover, it has been reported that hepatic ferroptosis plays an important role as the trigger for initiating inflammation in non-alcoholic steatohepatitis, showing that the expressions of TNF-α, IL-6, and IL-1β were significantly upregulated following ferroptosis." (PMID 37425328, 2023). "Since TNF-alpha is upregulated in the progression of nonalcoholic fatty liver disease (NAFLD) to non-alcoholic steatohepatitis (NASH), it is interesting to speculate that regulating the TNF-alpha release by targeting ADAM17 could serve as a therapeutic strategy to reduce liver inflammation." (PMID 38139236, 2023). "However, under some conditions, such as non-alcoholic steatohepatitis (NASH) or after liver transplantation much higher TNF levels may be measurable (34.2 and 43 ng/ml, respectively)." (PMID 28878689, 2017). "Individual studies and pilot trials of pentoxifylline in nonalcoholic steatohepatitis have suggested that anti-inflammatory therapy had effectively biochemical improvement and cytokine-mediated systemic inflammation amelioration (i.e., reduced plasma TNF-α and IL-6 levels)." (PMID 21477300, 2011). "In non-alcoholic steatohepatitis (NASH) mice, quercetin and its glycoside rutin were shown to reduce TNF-α and IL-6 inflammatory markers." (PMID 38225555, 2024). "In murine nonalcoholic steatohepatitis (NASH) model, both hepatic vagotomy and α7nAChR knockout upregulated pro-inflammatory cytokine (e.g., TNF-α, IL-12)." (PMID 38818213, 2024). "Our research group has previously demonstrated that DM509 treatment to non-alcoholic steatohepatitis mice decreased liver CXCR3, CXCL9, CXCL10, TNFα, IL-1β, and TGF-β expression." (PMID 38235144, 2023).
non-alcoholic steatohepatitis (continued). "In a murine model of non-alcoholic steatohepatitis, INT-767 significantly reduced pro-inflammatory cytokines production by macrophages such as IL-6 and TNF-a while increasing the anti-inflammatory cytokine IL-10." (PMID 37834329, 2023). "Together they promote the development of non‐alcoholic steatohepatitis (NASH) characterized by liver inflammation and activated inflammatory cytokine signaling pathways stimulated by TNF‐α, IL‐1β, KC/CXCL1, MCP1/CCL2, and others." (PMID 35830259, 2022). "Patients with NAFLD and nonalcoholic steatohepatitis (NASH) present higher levels of TNF and TNF-messenger ribonucleic acid (mRNA) compared to healthy subjects." (PMID 34063052, 2021). "Cytokines such as TNF-α and TGF-β from Kupffer cells (KCs) are required for the development of nonalcoholic steatohepatitis (NASH)." (PMID 25984739, 2015). "Likewise, in an HFD-induced nonalcoholic steatohepatitis (NASH) murine model, KMF attenuated hepatic injury by inhibiting neutrophil-mediated inflammation and reducing the production of TNF-α and IL-1β." (PMID 40918131, 2025). "Previous reports indicate that NF-κB transcriptional activation leads to increased releases of several inflammatory cytokines including tumor necrosis factor-α (TNF-α), interleukin-6 (IL-6), and IL-1β in Kupffer cells as observed in non-alcoholic steatohepatitis (NASH) livers." (PMID 28165393, 2017). "In models of nonalcoholic steatohepatitis (NASH), GLP-1 analogs have been shown to attenuate hepatic inflammation by reducing M1 macrophage infiltration and inhibiting NF-κB activity, thereby lowering the expression of pro-inflammatory mediators such as IL-6, TNF-α, and iNOS." (PMID 41019986, 2025). "Another study of 28 participants with non-alcoholic steatohepatitis (NASH) showed that 420 mg A. cinnamomea mycelium daily for 3–6 months significantly reduced liver steatosis and TNF-α levels without adverse events, demonstrating its hepatoprotective efficacy." (PMID 40238365, 2025). "While we did not observe increased inflammation in the liver on a high-fat diet based on p65 phosphorylation, TNF-α expression, or IL-1β expression, this is likely because 8 weeks on a HFD primarily leads to an NAFLD phenotype rather than progression to non-alcoholic steatohepatitis." (PMID 37432201, 2023).
experimental autoimmune encephalomyelitis (96 papers, 2008 to 2025). An autoimmune demyelinating disease of the central nervous system that is produced experimentally in animals by the injection of homogenized brain or spinal cord in Freund's adjuvant. "Hence, it has been reported that in VPAC2-deficient mice with experimental autoimmune encephalomyelitis, proinflammatory cytokines (TNF-α, IL-6, IFN-γ (Th1), and IL-17 (Th17)) increased, and anti-inflammatory cytokines (IL-10, TGF-β, and IL-4 (Th2)) decreased." (PMID 36101343, 2022). "In mice, TNFα signalling in the DRG was recently shown to be sexually dimorphic in an experimental autoimmune encephalomyelitis model." (PMID 39713351, 2025). "Specifically, Tlr4-mediated NF-κB activation drives the upregulation of proinflammatory cytokines (IL6, IL1β, and TNFα), which is consistent with its role in amplifying microglial reactivity in experimental autoimmune encephalomyelitis." (PMID 40563324, 2025). "In a pathological example, microglia promote tissue damage in experimental autoimmune encephalomyelitis by secreting pro-inflammatory cytokines, such as TNFα, IL-6, and GM-CSF, at the peak of inflammation." (PMID 38048364, 2023). "Microglia-specific TAK1 KO mice showed decreased expression and release of IL-1β and TNF-α in CNS in animal models of experimental autoimmune encephalomyelitis and experimental stroke." (PMID 36862288, 2023). "Neuro-inflammatory animal models such as experimental autoimmune encephalomyelitis, intravitreal injection of the cytokines (TNFα, TNF/3, IL-1, IL-6, Interferon), and chronic nerve compression model are well known." (PMID 37239226, 2023). "In the context of experimental autoimmune encephalomyelitis, we recently observed TNFα-induced neuronal hyperactivity during the remission phase, ultimately leading to neuronal death and behavioral abnormalities." (PMID 35587822, 2022). "In the same line, recent findings in an experimental autoimmune encephalomyelitis (EAE) model show that acute pharmacological SIRT6 inhibition decreases TNFα secretion." (PMID 35150745, 2022). "Low level (5 μg) of administration of L654 for 5 days significantly reduced circulating TNF-α and dramatically reduced disease severity in the experimental autoimmune encephalomyelitis model." (PMID 35278409, 2022). "Nevertheless, the ability of DcR3 to upregulate IL-4 and IL-10 but simultaneously downregulate IFN-γ, IL-12, TNFα, and IL-17 after influenza hemagglutinin peptide stimulation and in the experimental autoimmune encephalomyelitis model was demonstrated." (PMID 33746978, 2021). "Accordingly, the blockage of TNF signaling in the experimental autoimmune encephalomyelitis (EAE) mice ameliorated the clinical score, reducing both synaptic alterations and dendritic loss." (PMID 33007809, 2020). "Among others, tumor necrosis factor (TNF) represents a proinflammatory molecule critically involved in the pathogenesis of both animal models of disease (i.e., experimental autoimmune encephalomyelitis, EAE) and of human MS." (PMID 30761069, 2019). "E2 has been shown to downregulate TNF production and reduce the severity of experimental autoimmune encephalomyelitis in cytokine knockout mice." (PMID 28882159, 2017). "Pathological levels of IL1β impede synaptic long-term potentiation whereas elevated TNFα contributes to early synaptic abnormality in somatosensory cortex in mouse models of experimental autoimmune encephalomyelitis." (PMID 28769762, 2017). "Increased TNF in the central nervous system (CNS) of animals undergoing experimental autoimmune encephalomyelitis (EAE), a rodent model of MS, supports pro-inflammatory and disease enhancing activity." (PMID 26906225, 2016). "The deleterious effect of TNF in MS has been further emphasized by animal studies showing that TNF inhibition reduced the severity of experimental autoimmune encephalomyelitis (EAE) symptoms." (PMID 24587232, 2014).